DPP4 (dipeptidyl peptidase 4)
Diseases named in the same sentence as DPP4 in open-access papers (continued):
Sharing a sentence is not in itself a finding about the gene and the disease.
tumor (continued). "Subsequent qRT-PCR analysis also showed that the expression level of CD44, DPP4 and SLC7A11 in ccRCC samples are significantly higher than that in paired non-tumor samples." (PMID 34370716, 2021). "The heatmap showed that more than half of the genes were downregulated in tumor tissue, and consistent with the univariate Cox regression analysis, they represented a better prognosis, including PTGS2, ACO1, DPP4, CRYAB, PRKCA, ACSL4 and AKR1C3." (PMID 34475496, 2021). "DPP-4-kd 4T1 tumors exhibited increased expression of P-gp, ABCG2 and MRP1 in primary tumors compared with that of control tumor-bearing mice, and this trend was enhanced in the presence of DOX." (PMID 31991851, 2020). "Proof-of-concept in a mouse model showed that the Sitagliptin-mediated DPP4 inhibition enhanced the tumor rejection by preserving the agonist form of CXCL10 and increasing the trafficking into the tumor by the CXCR3 expressing lymphocytes." (PMID 30026741, 2018). "Recently, a study shows that the inhibition of DPP4 will increase CD4+ and CD8+ T lymphocytes and delayed tumor growth." (PMID 27936466, 2017). "Sensitivity of DPP4 for malignant follicular tumours including the FVPTC was low with a misdiagnosis rate of 20–30%, especially with tumours presenting Hürthle or tall-cell features." (PMID 18212751, 2008). "Additionally, the inhibition of dipeptidyl peptidase-4 (DPP4/CD26) promotes eosinophil infiltration into solid tumors by increasing CCL11 levels, leading to significant suppression of tumor growth." (PMID 40721870, 2025). "Additionally, in LUAD, TCP11L2 was the only protein decreased in the tumor samples, and in LUSC, CAB39, DEPDC1B, DPP4, PDPK1, and POLD4 were significantly down-regulated." (PMID 39949782, 2025). "While DPP-4 inhibition did not directly induce tumor cell death or alter activation/exhaustion markers in tumor-infiltrating CD8+ T cells, it stimulated splenic T cell proliferation in vitro." (PMID 40565099, 2025). "Moreover, DPP4 was found to be engaged with other CD26 homologous cell surface proteases, such as MMPs and FAPα, and expressed in tumor cells, malignant transformation, and cancer progression, thereby facilitating invasion." (PMID 39001488, 2024). "Previous studies have reported the negative impact of DPP4 on anti-tumor immunity, where inhibiting DPP4 can enhance the efficacy of tumor immunotherapy." (PMID 39232806, 2024). "In view of the important regulatory role of DPP4 inhibitors in the TME, we speculate that this type of drugs has great potential in tumor immunotherapy." (PMID 37115489, 2023). "IHC staining for DPP4 expression in tumor tissues showed that DPP4 was expressed in the stromal tissues of all nude mice implanted with tumor cells, suggesting that only CXCL10 produced by the implanted cells was inactivated by DPP4." (PMID 37218983, 2023). "DPP4 inhibitors preserve the activity of CXCL10 and make biologically active CXCL10 interact with its ligand (CXCR3) on NK and T cells, thereby increasing the chemotaxis of NK and T cells and further inhibiting tumor growth." (PMID 37115489, 2023). "In contrast, other reports demonstrated the opposite results, such as decreased membrane-bound DPP4 activity in RCC and correlation of high soluble DPP4 activity (measured in tumor tissue homogenates) with tumor aggressiveness and poor survival of RCC patients." (PMID 37563650, 2023). "Considering the potential role of DPP4 inhibitors as additional therapeutic agents in current HCC treatment, it should also be noted that the combination of a DPP4 inhibitor (sitagliptin) and an anti-PD1 antibody improved anti-tumor immunity in immunocompetent mice." (PMID 35053615, 2022).
tumor (continued). "DPP4 also has other non-enzymatic functions that are unrelated to its dipeptidase activity, in which it interacts with different partners and sustains tumor growth, invasion, and metastasis." (PMID 35053615, 2022). "In GC, this positive effect on tumor cell proliferation of CAFs might be mediated by CAF-released dipeptidyl peptidase-4 (DPP-4) and its receptor, C-X-C chemokine receptor 4 (CXCR4), which is present in tumor cells." (PMID 36244987, 2022). "In their study, DPP4 inhibition with sitagliptin was shown to increase eosinophil migration into the tumors, and the anti-tumor activity of eosinophils was shown to be independent of T-cells." (PMID 35954493, 2022). "Comparison of tumor growth in DPP4−/− mice with that in their heterozygous littermates revealed a significant delay in tumor growth when DPP4 was absent, indicating that DPP4 plays a role in tumorigenesis." (PMID 35053615, 2022). "Although this type of chemokine induction is totally different from that induced by DPP4 inhibitors, 2-DG-PLGA-NPs also enhance CD8+ T cell infiltration into liver tumors, and not only amplified the anti-tumor effects induced by the anti-PD1 antibody but also suppressed anti-PD1-resistant tumors." (PMID 35053615, 2022). "Notably, administration of a DPP4 inhibitor resulted in higher concentrations of the chemokines CCL11, interleukin (IL)-4, IL-5, and IL-33 in tumor extracts and increased migration of eosinophils into solid tumors." (PMID 35053615, 2022). "Similar results were found for DPP4 activity comparing no neoplasia, AA, and CRC (ANOVA test, p-value < 0.001)." (PMID 36230486, 2022). "Since recent studies have shown the efficacy and tolerance of sitagliptin as cancer therapeutic, it would be interesting to further investigate its activities as a target for DPP4/CTNNB1/MET signaling pathways in THCA, both in vitro and in vitro in tumor-bearing mice." (PMID 35205190, 2022). "However, FANCD2, SLC7A11, GLS2, DPP4, and ALOX15 were obviously suppressed in grades 1–3 of tumor samples compared to normal tissues." (PMID 34531924, 2021). "Increased DPP4 expression mediates high CD44 and FAP-α expression, which could exert suppressive effects on tumor growth and metastasis." (PMID 34955820, 2021). "DPP-4 in the primary tumor may have an essential role in regulating cancer biology, and DPP-4/CD26 has also been noted as a potential biomarker of tumor progression." (PMID 34063285, 2021). "On the other hand, moderate and strong staining patterns for CD44, DPP4, and SLC7A11 were observed in the cytoplasm and cell membrane of tumor tissues, while NCOA4 only exhibited weak positive staining on the cell membrane of tumor tissues." (PMID 34370716, 2021). "Flow cytometric analysis for CD26 (Dpp4) and CD34 expression confirmed that iCAFs represent a substantial fraction of the EYFP+ PDPN+ tumor fibroblasts and that the subsets of Ly6C+ CD34+ and Sca-1+ CD34+ fibroblasts were significantly expanded after artLCMV treatment." (PMID 34354077, 2021). "Here, especially effects of CD26/DPP4 inhibition on the immune system are discussed to potentially affect tumor incidence rather than direct pro-tumorigenic effects on healthy cells." (PMID 34885056, 2021). "DPP-4 expression in the primary tumor may regulate cancer behavior; however, the expression of DPP-4 in the primary tumor appears to be the heterogeneity patterns, depending on tumor type, stage, microenvironment, and host condition." (PMID 34063285, 2021). "Currently, it is not easy to exactly determine the role of DPP4 in carcinogenesis, since it can act as a tumor promoter or suppressor and its role is essentially dependent on tumor type and localization, cell type and microenvironment." (PMID 33525607, 2021). "The administration of a DPP4 inhibitor in mice with subcutaneous EMT6 breast cancer cell implantation induced intratumoral accumulation of CCL11, resulting in eosinophilic chemotaxis and reduced tumor growth." (PMID 34572273, 2021).
tumor (continued). "In 19 MM cases, statistically significant correlation between variation in pre/post day 29 serum DPP4 titer and tumor volume was observed by SRDC analysis, while the correlation between day 29pre serum sCD26 titer and tumor volume almost reached statistical significance (p = 0.065) by PPMC analysis." (PMID 33757558, 2021). "Different studies highlighted that inhibition of tumor progression also occurred in the absence of DPP4 enzymatic activity, as an increased DPP4 gene expression being sufficient enough to revert the malignant tumor phenotype." (PMID 33525607, 2021). "Comparing tumour and non-tumour diseased tissue, we observed a modest increase in DPP4 expression by CD4+ T cells (CD45+ CD3+ CD4+ CD8− NK1.1−) and NK cells (CD45+ NK1.1+ CD3−)." (PMID 34771657, 2021). "Interestingly, preliminary data also indicate that treatment with the CD26/DPP4 inhibitor sitagliptin impaired the migration of CD26hi mesothelin-specific CAR T cells, thus limiting tumor infiltration by CD26hi T cells resulting in impaired tumor control." (PMID 34885056, 2021). "In CD-1 mice, DPP4 inhibition did not induce dysplasia in the colon and showed no tumor-promoting activities." (PMID 32498358, 2020). "Therefore, we further explored DPP4 expression in subgroups of TNM stage, tumor number, and vascular invasion." (PMID 32294701, 2020). "Furthermore, the dipeptidyl peptidase (DPP)-4 inhibitor, KR62436, promoted primary tumor growth, and lung metastasis via induction of the CXCL12/CXCR4/mTOR/EMT signaling axis in a syngeneic mouse model." (PMID 32245205, 2020). "Indeed, a number of inflammatory mediators with central roles in immune suppression and tumour progression (e.g., CCL5, 11, 22; CXCL2, 6, 9–12) are potential targets for DPP4-directed cleavage." (PMID 33143089, 2020). "In conclusion, expression of DPP4 protein decreased in HCC tissues and may indicate worse OS of HCC patients after surgery; DPP4 may act as a tumor suppressor gene for HCC." (PMID 32294701, 2020). "Furthermore, DPP4 expression had an inverse correlation with the aggressiveness of HCC, such as the TNM state, tumor number, and microvascular invasion." (PMID 32294701, 2020). "Therefore, targeted inhibition of DPP4 may delay resistance to EGFR‐TKIs and eradicate residual tumor cells." (PMID 40479551, 2025). "Collectively, these data confirm that nanobody-DPP4 fusions primarily exert their therapeutic effects by disrupting sICOSL-mediated suppressive immune microenvironments, rather than by directly impacting tumor proliferation." (PMID 40708008, 2025). "The residual activity after DPP4 inhibition could be attributable to other prolyl endopeptidases such as PREP (PREP), which also exhibited high activity in tumor samples, especially in long-term survivors converging with dd-ABPP." (PMID 40425563, 2025). "In addition, tumor size, stage, and proliferation in HCC were related to DPP-4 enzyme level." (PMID 40786041, 2025). "Moreover, DPP-4i could have anti-cancer effects by modulating the DPP-4/SDF-1/CXCR4 axis and the immune balance, enhancing tumor rejection by preserving biologically active CXCL10 and increasing trafficking into the tumor by lymphocytes." (PMID 40175622, 2025). "Specific genes downregulated in HG tumours which showed significantly higher promoter methylation included the developmental transcription factors CDX1, CDX2, GATA6, HNF1A, the marker of colonic differentiation, DPP4, and the markers of LGR5+ intestinal stem cells, ASCL2, LGR5." (PMID 40473896, 2025). "Dipeptidyl peptidase-4 (DPP-4/CD26), a cell surface glycoprotein involved in various biological functions ranging from immune regulation to glucose metabolism, also plays a role in carcinogenesis, either suppressing or activating tumors relying on the tumor microenvironment." (PMID 39390508, 2024). "They suggested that the circulating DPP-4 does not come from the tumor tissue of OSCC patients." (PMID 39390508, 2024).
tumor (continued). "However, similar to our findings, their study did not reveal any significant differences in DPP-4 levels concerning tumor size or lymph node involvement." (PMID 39390508, 2024). "DPP-4 displays numerous biological functions in tumor and nontumor cells." (PMID 37760498, 2023). "Regarding the induction of DPP4 via the circMET/miR-30-5p/Snail axis in HCC tissues, implantation of C57/BL/6 mice with circMET-transfected Hep1-6 cells was reported to induce an immunosuppressive tumor microenvironment with significant suppression of tumor-infiltrating CD8+ T cells." (PMID 35053615, 2022). "In this eosinophil-mediated anti-tumor response, CCL11, an eosinophil-selective chemokine in the ‘eotaxin subfamily,’ was demonstrated to be cleaved by DPP4 into a truncated form (CCL113–74) with diminished chemoattractant properties, as found for CXCL10 cleavage by DPP4." (PMID 35053615, 2022). "Thus, CORO1A, DPP4 and ANXA5 might play the significant roles in some common biological process of tumor." (PMID 33407865, 2021). "A study showed that decreased expression of DPP4 in NSCLC cells indicated its tumor suppressor effect, which might be independent of its enzymatic activity." (PMID 34955820, 2021). "Previous preclinical studies indicated that DPP-4 inhibitors could accelerate tumor growth and metastasis, not only the potential cancer-protective effects." (PMID 34063285, 2021). "Due to the critical role of DPP4 in immunometabolism, our results indicate that pharmacological inhibition of DPP4 might provide beneficial therapeutic effects for SARS-CoV-2 treatment together with other strategies in specific tumor patients." (PMID 33614513, 2021). "The tumours were analysed via flow cytometry for the simultaneous expression of six CAF markers: alpha smooth muscle actin (αSMA), fibroblast activation protein alpha (FAPα), platelet derived growth factor receptor alpha and beta (PDGFRα and PDGFRβ), CD26/DPP4 and podoplanin (PDPN)." (PMID 34016130, 2021). "In addition, examination of background factors between SD and PD cases indicated that no bias was found in age, BMI, absolute value of tumor volume or serum sCD26/DPP4 titer before YS110 administration, except for gender (data not shown)." (PMID 33757558, 2021). "Instead, local use of dipeptidyl peptidase-4 (DPP4) inhibitors to block CXCL12-inactivating enzymes may be hypothesized to locally increase the ligand levels and further validate this role of this chemokine in impairing tumor progression toward metastasis." (PMID 34834449, 2021). "Dipeptidyl peptidase-4 (DPP4), also known as cluster of differentiation 26 (CD26), is a commonly expressed cell surface protein found in many cell types that can function as a tumor suppressor or activator, depending on the cancer type and its interactions with the tumor microenvironment (TME)." (PMID 34055551, 2021). "However, current clinical evidence is not sufficient to evaluate potential tumor-promoting or tumor-suppressive effects of CD26/DPP4 inhibition and functional explanations are still missing." (PMID 34885056, 2021). "Due to its pleiotropic potential, this research is focusing on understanding whether sitagliptin, a DPP-4 inhibitor, has a positive or negative influence on tumor progression." (PMID 33256016, 2020). "It is reasonable that there is the threshold for ABC transporter to gain chemoresistance; ABC transporter levels in DPP-4-kd tumor in some mice could not be sufficient enough to reach the threshold to induce chemoresistance." (PMID 31991851, 2020). "Our analyses imply that the anti-tumor activities of DPP4i in solid tumors are unlikely to be solely due to immunologic modulation, as these effects of DPP4i should not be dependent on the expression levels of DPP4 on the organ tissue." (PMID 32296640, 2020). "A recent study confirmed that DPP4 inhibition did not increase tumor occurrences but may promote the metastasis of multiple cancer cell lines." (PMID 32498358, 2020).
tumor (continued). "Whether PI3K-stimulating hypoglycemic agents (such as insulin, sulfonylureas, DPP4-inhibitors/GLP-1 agonist, or meglitinides) can be used without risk of tumor growth is another area in need of more research." (PMID 28856166, 2017). "Therefore, the combined mRNA expression of key signal transduction pathway components and regulators of the extracellular tumor microenvironment in combination with certain direct regulators of immune activity (ICOS, DPP4) appears to predict priming for responsiveness to CTLA-4 blockade." (PMID 28807052, 2017). "In addition, most reports about the correlation between DPP-4 expression in tumor and cancer prognosis did not mention whether patients had diabetic conditions or not." (PMID 34063285, 2021). "Conversely, protein levels of these enzymes (e.g. FASN, DPP4, PREP, ELANE) showed only weak or no changes between tumors and nontumor adjacent-tissues, resulting in substantially less accurate tumor classification (right)." (PMID 40425563, 2025). "In adenocarcinoma, both DPP4 and PSA were more highly expressed in the tumor than in normal lung tissue (n = 3)." (PMID 35650221, 2022). "In this FIT positive sub-cohort, 116/198 individuals with no neoplasia (excluding NAA) were correctly classified as negative according to sCD26 (58.59%), 87/148 (58.78%) for DPP4, and 71/146 (48.63%) for the sCD26/DPP4 ratio." (PMID 36230486, 2022). "Unlike its family member DPP4, the role of DPP3 in tumor biology is much less clear." (PMID 38655619, 2024). "However, the effects of CD26/DPP4-mediated HMGB1 processing on its anti-bacterial and anti-tumor effects and its regulated release have not been analyzed so far." (PMID 34885056, 2021). "DPP4 enzymatic activity has been shown to reduce both T‐cell and eosinophil migration to sites of tumor by inactivating the T‐cell chemokine CXCL10[8b] and the eosinophil chemokine CCL11.[8c] Here, we extended these findings by showing the nonenzymatic activity of DPP4 in cell migration." (PMID 36683148, 2023). "Similarly, DPP4 expression was much lower in the HCC tissues from patients with multiple tumors and the presence of microvascular invasion compared to patients with a single tumor (P=0.0335) and no microvascular invasion (P=0.0064)." (PMID 32294701, 2020).